AMZ1 (archaelysin family metallopeptidase 1)
Description:
Probable zinc metalloprotease.
Synonyms: KIAA1950
Tractability: No criterion of Open Targets' tractability assessment is met for any kind of drug.
Gene: Protein-coding gene on chromosome 7 (2,679,276 to 2,775,500, forward strand). Ensembl gene ENSG00000174945.
Gene Ontology:
Molecular function: metallopeptidase activity; peptidase activity
Biological process: proteolysis
Genetic constraint (gnomAD): Loss-of-function variants: 41 observed, 27.27 expected, observed/expected ratio (o/e) 1.5, 90% interval 1.17 to 1.88. The synonymous counts are far from expectation, so gnomAD's model fits this gene poorly and the ratio says little. Missense variants: 1,041 observed, 645.9 expected, observed/expected ratio (o/e) 1.61, 90% interval 1.53 to 1.7. Synonymous variants: 458 observed, 292.13 expected, observed/expected ratio (o/e) 1.57, 90% interval 1.45 to 1.69.
Homologues: Orthologues: chimpanzee AMZ1 (99% identical), macaque AMZ1 (95% identical), guinea pig AMZ1 (77% identical), pig AMZ1 (77% identical), rat Amz1 (76% identical), mouse Amz1 (74% identical), rabbit AMZ1 (65% identical). Paralogues in human: AMZ2 (25% identical).
Diseases named in the same sentence as AMZ1 in open-access papers:
AMZ1 is named in the same sentence as 6 diseases in open-access papers, as found by Europe PMC text mining. Sharing a sentence is not in itself a finding about the gene and the disease. The quoted sentences say what the papers report.
Chagas disease (1 paper, 2018). A parasitic infection caused by Trypanosoma cruzi. "Archaeal microvesicles and their exosomes, possibly associated with release of archaeal AMZ1 in heart failure, are future candidates of heart failure biomarkers if confirmed in larger series, and the therapeutic focus in the treatment of Chagas disease." (PMID 30519544, 2018).
Dyskinesia (1 paper, 2022). A movement disorder which consists of effects including diminished voluntary movements and the presence of involuntary movements. "On the basis of a monozygotic twin model, a study suggested that the demethylation of AMZ1 in DLPFC is associated with dyskinesia, another potential symptom of AD." (PMID 35585924, 2022).
heart failure (1 paper, 2018). Inability of the heart to pump blood at an adequate rate to meet tissue metabolic requirements. "Flow cytometer showed higher numbers of AMZ1 microvesicles in indeterminate form (64 vs. 36, P = 0.02) and higher archaeal DNA microvesicles in heart failure (8.1 vs. 0.9, P < 0.001)." (PMID 30519544, 2018). "A positive correlation between exosomes and AMZ1 content was seen in indeterminate form (r = 0.5, P < 0.001), but not in heart failure patients (r = 0.002, P = 0.98)." (PMID 30519544, 2018).
AMZ1 also shares sentences with these, for which no sentence is quoted: cancer (1 paper); Candidemia (1); osteoporosis (1).